S1PR3 (sphingosine-1-phosphate receptor 3)
Diseases named in the same sentence as S1PR3 in open-access papers (continued):
Sharing a sentence is not in itself a finding about the gene and the disease.
interstitial lung disease (1 paper, 2022). A diverse group of lung diseases that affect the lung parenchyma. "Notably, the majority of patients with positive S1PR2-aAb (60.7%) or S1PR3-aAb (71.9%) displayed interstitial lung disease." (PMID 35860272, 2022).
ischemia reperfusion injury (1 paper, 2017). Adverse functional, metabolic, or structural changes in ischemic tissues resulting from the restoration of blood flow to the tissue (reperfusion), including swelling; hemorrhage; necrosis; and damage from free radicals. "Multiple studies demonstrated a protective effect in ischemia-reperfusion injury using fingolimod (agonist for S1PR1, S1PR3, S1PR4, and S1PR5) in different organs including the heart." (PMID 28596734, 2017).
leiomyoma (1 paper, 2022). A well-circumscribed benign smooth muscle neoplasm characterized by the presence of spindle cells with cigar-shaped nuclei, interlacing fascicles, and a whorled pattern. "Similarly, S1PR2, S1PR3, and S1PR5 mRNA levels were significantly higher in uterine fibroids in comparison with myometrial healthy tissues; both S1PR2 and S1PR3 protein levels were also elevated in the leiomyoma." (PMID 36362323, 2022).
liver failure (1 paper, 2025). A liver disease characterized by the liver losing or has lost all of its function. "Indeed, in LPS/D-galactosamine (D-Gal)-induced liver failure, S1P levels were elevated, whilst the expression of SphK1, S1PR1, and S1PR3 was upregulated in the liver, and the levels of serum markers of liver failure, AST and ALT, and the serum cytokines TNF-α, IL-1, and IL-6 were increased." (PMID 39935473, 2025).
muscular atrophy (1 paper, 2024). The loss of muscle tissue due to inactivity or disease. "In the mdx animal model, genetic excision of S1PR3 dramatically hindered the process of muscular atrophy, suggesting that S1PR3 may inhibit muscle differentiation." (PMID 39404384, 2024).
nasopharyngeal carcinoma (1 paper, 2019). A carcinoma arising from the nasopharyngeal epithelium. "Consistently associated with Epstein-Barr virus infection, the pathogenesis of nasopharyngeal carcinoma has also recently been linked to S1P/S1PR3 signaling." (PMID 31807117, 2019). "S1PR3 mRNA is overexpressed in Epstein–Barr virus-positive nasopharyngeal carcinoma patient-derived xenografts and some primary nasopharyngeal carcinoma tissues and its knockdown blocks both AKT activation and the migration of nasopharyngeal carcinoma cells induced by S1P." (PMID 31807117, 2019).
osteomyelitis (1 paper, 2023). An acute or chronic inflammation of the bone and its structures due to infection with pyogenic bacteria. "In our present study, we have observed that the benefit of S1P lyase inhibition on bone regeneration in posttraumatic osteomyelitis was abolished in S1PR3 deficient mice." (PMID 37710406, 2023).
posttraumatic stress disorder (1 paper, 2023). "Importantly, this study also observed decreased S1PR3 mRNA expression in the blood of war veterans with posttraumatic stress disorder (PTSD), and its expression negatively correlated with symptom severity." (PMID 37628815, 2023).
prostate carcinoma (1 paper, 2023). A carcinoma that arises from epithelial cells of the prostate gland. "S1PR3 expression level was higher in AA than EA prostate cancer patients whereas GALR1, CHRM3, and NPFFR1 expression level was lower in AA than EA prostate cancer patients." (PMID 36937425, 2023).
Psoriasiform dermatitis (1 paper, 2025). A skin abnormality characterized by redness and irritation, with thick, red skin that displays flaky, silver-white patches (scales). "To elucidate whether the improved psoriasiform dermatitis observed in S1pr3-KO mice was due to a reduction in STAT3 in keratinocytes, we then investigated the mechanistic link between S1PR3 and STAT3 signaling in HaCaT keratinocytes." (PMID 39833165, 2025).
Salmonella Infections (1 paper, 2023). Infections with bacteria of the genus SALMONELLA. "Furthermore, we found that inhibition of S1PR3 enhanced dsDNA-induced AIM2 inflammasome and salmonella infection-induced NLRC4 inflammasome activation, as indicated by enhanced caspase-1 cleavage." (PMID 36798132, 2023).
spinal cord ependymoma (1 paper, 2021). An ependymoma that arises from the spinal cord. "While the S1PR3 gene expresses in endothelial cells and contributes to angiogenesis regulation, their study suggested that co-amplification of the SHC3 and S1PR3 genes is connected with ependymomal tumor survival and growth in both posterior fossa and spinal cord ependymomas." (PMID 34203272, 2021).
thyroid follicular carcinoma (1 paper, 2019). "Several studies reported that S1P–increased HIF1α expression was abolished by S1PR1/S1PR3 inactivation or S1PR3 silencing in liver hepatocellular carcinoma cells and thyroid follicular carcinoma cells, respectively." (PMID 31383843, 2019).
tumor (56 papers, 2009 to 2026). "Next, the transwell assay found that TY52156 markedly weakened the capacities of migration and invasion of TSC2-deficient cells, indicating that inhibition of S1PR3 reduced the metastatic capacity of tumor cells." (PMID 36543771, 2022). "GNAQ and S1PR3 mutations were shared in both tumor and normal sites." (PMID 38254245, 2024). "Considering the critical role of angiogenesis in tumor progression and the need for multi-target therapies to overcome drug resistance, S1PR3 antagonism via pepducins presents a promising strategy, particularly in S1P-driven malignancies like OS." (PMID 40137142, 2025). "S1PR3 antagonism or knockdown was shown to reduce tumour size, whereas SPHK1 overexpression exacerbated tumour growth." (PMID 41253780, 2025). "S1P has five high affinity receptors, and it is generally believed that S1PR1 and S1PR3 promote tumor cell migration and survival." (PMID 38446289, 2024). "Similar to S1PR2 so far most studies addressing the function of S1PR3 in cancer concentrated on its role in tumor cells." (PMID 35163211, 2022). "Collectively, these data illustrate that inhibition of SPHK1 or S1PR3 triggers autophagic death in tumor tissues and slows the occurrence and development of tumors." (PMID 36543771, 2022). "In cancer stem cells (CSCs) or tumor-initiating cells, SPHK1 expression enhanced tumor formation via Notch activation stimulated by S1PR3 in both in vitro and in vivo studies." (PMID 35565311, 2022). "Studies have found that S1PR3 plays a role in cell inflammation, cell proliferation, cell migration, tumor invasion, I/R, tissue fibrosis, and vascular activity." (PMID 35242008, 2022). "There, it was shown that S1P/S1PR3 signaling is a potent driver for tumor cell migration, proliferation, angiogenesis, and metastasis in different tumor entities such as lung and breast cancer." (PMID 35163211, 2022). "In a mouse BC xenograft model, BBP increased the incidence of lung metastasis and this effect was reversed with SPHK1 or S1PR3 knockdown tumor cells." (PMID 33203443, 2020). "It has been reported that there were upregulation of S1PR1, S1PR2, and S1PR3 expressions in tumor tissues compared with normal margins in a subpopulation of Iranian BC patients." (PMID 32253828, 2020). "The balance of the effect of S1P on S1PR1 and S1PR3 in the activity of MDSC in tumor niche requires further studies." (PMID 29467963, 2018). "Specifically, targeting S1PR3 may disrupt tumor-supporting vascular branching, offering a novel approach to impair cancer progression." (PMID 40137142, 2025). "In conclusion, based on our findings, S1PR3 emerges as a critical regulator of endothelial cell differentiation and vascular morphogenesis, with inhibition exerting more pronounced effects on endothelial versus tumor cells." (PMID 40137142, 2025). "S1PR3 inhibition functionally tightens the blood–tumor barrier (BTB) in vitro and in vivo." (PMID 35685645, 2022). "Moreover, IHC staining showed that the higher expression level of S1PR3 was detected in NSCLC specimens compared with the adjacent control, and the S1PR3 level was also proven to be positively correlated with tumor progression." (PMID 36361531, 2022). "In summary, whereas S1PR3 activation on tumor cells would most likely worsen cancer prognosis, an immune cell specific S1PR3 agonist might serve as a potential pharmacological drug to enhance anti-tumor immune response." (PMID 35163211, 2022). "The S1P/S1PR3 axis is considered to promote tumor cell proliferation, migration and angiogenesis." (PMID 36506313, 2022). "Because S1PR3 downstream signalling promotes M2 macrophage polarization, using an S1PR3 antagonist in the tumour microenvironment may block the formation of M2 macrophages and fundamentally reduce the possibility of bone metastasis." (PMID 32155312, 2020).
tumor (continued). "However, because the therapeutic efficacy of suppression or gene knockout of S1PR1 or S1PR3 varies widely for different types of tumors (currently only in tumor models or cells), further preclinical and even clinical trials are necessary." (PMID 31807117, 2019). "In our studies, targeting the SPHK1/S1PR3 axis with inhibitors reduced the expression of SPHK1 and S1PR3 and the biosynthesis of S1P (data now shown), significantly suppressed TSC2-deficient cells metastasis and prolonged the survival of mice carrying xenograft tumor." (PMID 36543771, 2022). "In addition, the involvement of S1PR3 has been demonstrated in tumor growth." (PMID 36506313, 2022). "Moreover, they showed that tumor development in cancer stem cells could be inhibited by administering S1PR3 antagonist or S1PR3 knockdown." (PMID 33920887, 2021). "For example, FTY720, an S1P modulator that binds to S1PR1, S1PR3, S1PR4, and S1PR5, has been shown to inhibit tumor growth and aggressiveness in various cancer models." (PMID 37744269, 2023). "Contrary to the pro-tumor roles of S1PR1, S1PR2, and S1PR3, S1PR5 was claimed to exert inhibitory effects on the proliferation and migration of esophageal cancer via the Ras/ERK, PI3K/Rac and Rho/ROCK signaling pathways." (PMID 34831211, 2021). "For instance, FTY720, an S1P agonist that binds to S1PR1, S1PR3, S1PR4, and S1PR5, has been indicated to suppress the growth and aggressiveness of tumor in several cancer models." (PMID 31807117, 2019). "Stratifying patients by tumor histotype, we found that S1PR3 was more expressed in cancerous than non-cancerous lung tissues of ADK patients." (PMID 37446018, 2023). "Moreover, the analysis of the LGG cohort demonstrated a similar profile to S1PR1, S1PR2, S1PR3, and S1PR4, which are upregulated in tumor tissue, significantly so for S1PR2 and S1PR3." (PMID 37760448, 2023). "Taken together, our findings exhibit the vital role of the SPHK1/S1PR3/PBX1 axis in regulating the cell cycle of NSCLC, and targeting SPHK1 may develop a therapeutic effect in tumor treatment." (PMID 36361531, 2022). "Fingolimod, an agonist of four S1PRs (including S1PR1, S1PR3, S1PR4, and S1PR5), induces receptor internalization and exerts antagonistic effects, which could markedly reduce the tumor load and abrogate the NF-κB/IL-6/STAT3/S1PR1 cascade." (PMID 34831211, 2021). "Furthermore, targeting S1PR3 with the inhibitor TY-52156 reduced tumour burden and prolonged survival in T-ALL patient-derived xenografts in mice, suggesting S1PR3 may be a therapeutic target in this CSC-driven disease." (PMID 41253780, 2025). "In addition, stratifying patients by tumor histotype and according to the sex, we found that S1PR3 was more expressed in cancerous than non-cancerous lung tissues of female ADK patients." (PMID 37446018, 2023). "However, we do not exclude that, in OS, S1PR3‘s role may be more critical in cancer stem cells, which drive aggressive tumor phenotypes." (PMID 40137142, 2025). "S1PR1 is critical in the regulation of inflammatory processes driving neovascularisation, providing tumours with the nutrients and oxygen needed for cancer cell survival, with S1PR2 and S1PR3 having some compensatory functions in the absence of S1PR1." (PMID 35158806, 2022). "In this case, suppression of tumor survival showed a benefit from TY52156, but the effect of PF543 was not as dramatic as inhibiting S1PR3." (PMID 36543771, 2022).
cancer (36 papers, 2012 to 2026). A tumor composed of atypical neoplastic, often pleomorphic cells that invade other tissues. "Aside from normal cell types, S1PR3 is highly expressed in various cancer cells and was shown to stimulate cancer progression." (PMID 38698424, 2024). "A recent paper demonstrated that sphingosine-1-phosphate increases the expansion of cancer stem cells via S1PR3 by a ligand-independent Notch activation in breast cancer." (PMID 29343717, 2018). "S1PR3 promoted migration and mobility not only of cancer cells, but also of normal cells, including bone marrow-derived mesenchymal stem cells." (PMID 29385066, 2018). "Indeed, we observed that S1PR3 was highly expressed in iCCA compared with NT tissues, as described for lung and other cancers where activation of S1PR3 mediates cell migration, invasion, and proliferation." (PMID 40408281, 2025). "Similarly, the SPHK1/S1P/S1PR3 axis promoted the expansion of aldehyde dehydrogenase (ALDH)-positive cancer stem cells (CSCs) via ligand-independent Notch activation." (PMID 36361531, 2022). "Additionally, S1PR3 activation was shown to promote cancer progression in osteosarcoma and lung adenocarcinomas." (PMID 35565311, 2022). "It has been suggested that, like S1PR1, S1PR3 is also has a role in cancer metastasis." (PMID 35250559, 2022). "S1PR3 upregulation occurs in different cancers like breast cancer and brain tumor metastasis." (PMID 35250559, 2022). "S1PR3, a member of the S1P receptor family, plays an essential role in the relevant pathophysiological processes of inflammation, cell proliferation, cell migration, cancer cell invasion and metastasis, I/R, tissue fibrosis, and vascular tone." (PMID 35685645, 2022). "Furthermore, S1P/S1PR3/Notch signaling activation results in the expansion of cancer stem cells (CSC) in several types of cancers." (PMID 35625898, 2022). "In addition, PI3K/AKT signaling has been targeted in cancer therapeutics, and previous reports show that S1PR3 regulates the PI3K/AKT pathway." (PMID 34326314, 2021). "S1PR1, S1PR3, and S1PR4 have been linked to cancer proliferation thus far." (PMID 33758708, 2021). "Taking into consideration the reported higher levels of S1PR1/S1PR3 in cancer cells compared to normal surrounding cells, it is tempting to suggest that high extracellular S1P and low levels of S1PR1/S1PR3 might represent an anti-cancer requirement." (PMID 29385066, 2018). "Interestingly, we found five upregulated cancer-related genes (Epha3, Hjurp, Kif26, S1pr3 and Pde3B) that shared miRNAs with the HMGA1P7 transcript." (PMID 25268743, 2014). "In addition, S1P is involved in enhancing endocytosis and migration of mature dendritic cells through S1PR3, an event that may increase the immune response to cancer cells." (PMID 32799825, 2020). "S1P could also regulate cancer cell metabolism via S1PR3 by accelerating aerobic glycolysis." (PMID 32456134, 2020). "Once exported, S1P acts on S1PR3, which stimulates ERK1/2 of the RAS/RAF/MEK/ERK signal transduction pathway leading to cancer cell proliferation." (PMID 33758708, 2021). "Consistently, our results indicated that S1PR3 activated PI3K phosphorylation and enhanced cancer initiation and progression." (PMID 34326314, 2021). "For this purpose, we treated HCC1954 cells with an allosteric sphingosine 1-phosphate receptor-3 agonist (CYM-5441), which was shown to activate actin polymerization as well as increase cancer stem cell expansion in BC46,47." (PMID 33070155, 2020). "Therefore, the targeting of S1P1 and S1PR3 may have great therapeutic potential for cancer." (PMID 31807117, 2019). "Thus, a cancer promoting role was suggested for S1PR1 and S1PR3 subtypes, while S1PR2 presence demonstrated potential growth-limiting effects." (PMID 29385066, 2018). "The only significant correlation between the presence of cancer and S1P system mRNA expression levels was for S1PR3 that showed a positive correlation with the presence of cancer independent of COPD status(r = 0.41, p<0.05)." (PMID 26485657, 2015).
cancer (continued). "S1PR1 and S1PR3 are shown to be involved in migration and invasion of cancer cells, whereas S1PR2 plays inhibitory roles in migration and invasion of cancer cell lines and trophoblast cells." (PMID 25188412, 2014). "It is not unusual to observe the increased expression of S1PR3, although the S1PR1 is often lost or decreased in many cancer cells." (PMID 29385066, 2018). "Studies on SPHK1 inhibitors have made some progress, while no ideal SPHK1 inhibitor is currently used for treating cancer in the clinic, and there are also other compounds including S1PR1 and S1PR3 (VPC03090) or S1PR2 (AB1) antagonists under preclinical evaluation." (PMID 36361531, 2022).
infection (7 papers, 2013 to 2023). The state of being infected such as from the introduction of a foreign agent such as serum, vaccine, antigenic substance or organism. "S-1P is also capable of enhancing infiltration of pulmonary CD11b+ macrophages and expression of S-1P receptor-3 (S-1PR3) in the lungs during the course of infection." (PMID 32038629, 2019). "In addition, to demonstrate that SphK-1 and S1PR-3 are indeed involved in the development of ALI/ARDS, further work should focus on the same infection model performed in SphK-1- and S1PR-3-knockout mice." (PMID 31483837, 2019). "Neither the mRNA levels of S1PR1 nor S1PR3 were affected by infection with N. meningitidis MC58." (PMID 38033162, 2023). "Although expression of S1PR1 and S1PR3 was not altered during the 8h infection time course, both receptors may be involved in the interaction of N. meningitidis with BECs after the release of S1P." (PMID 38033162, 2023).
inflammation (2 papers, 2014 to 2018). Aberrant reaction of the microcirculation characterized by movement of fluid and leukocytes from the blood into extravascular tissues. "In the current study, we newly clarified the possible effects of S1P/S1PR3 axis on the expression of the CCL20 from the airway ECs and showed therapeutic effect of VPC23019 on airway eosinophilic inflammation." (PMID 30192865, 2018).
neurodegenerative disease (2 papers, 2019 to 2020). A disorder of the central nervous system characterized by gradual and progressive loss of neural tissue and neurologic function. "This suggested that S1pr3 may contribute to neurodegenerative diseases." (PMID 32599915, 2020).
psychiatric disorder (2 papers, 2019 to 2023). A disorder characterized by behavioral and/or psychological abnormalities, often accompanied by physical symptoms. "Together, these data identify S1PR3 as a regulator of stress resilience and reveal sphingolipid receptors as important substrates of relevance to stress-related psychiatric disorders." (PMID 31316053, 2019). "Together, our findings demonstrate that S1PR3 in the mPFC promotes resilience to stress and is a novel substrate of relevance to stress-related psychiatric disorders." (PMID 31316053, 2019). "Additionally, specifically targeting S1PR3 pharmacologically may have therapeutic potential for treating stress-related psychiatric disorders and/or inflammatory disorders." (PMID 31316053, 2019).
bacterial infection (1 paper, 2015). "The relative MoDC vs. Mo/MP signature encompasses additional genes that participate in “migration of cells” (p = 10−2.3, with S1PR3, CCL17, and SLC2A1), “bacterial infection” (p = 10−3.2, with CD1B, CD209, and FCGR2B), and “synthesis of nitric oxide” (10−2.5, with PLAU, IL1R2, and NOS2)." (PMID 26150816, 2015).
hematologic malignancies (1 paper, 2025). "Indeed, a number of recently developed small molecule modulators selectively targeting S1PR2 or S1PR3, some with extensive clinical testing, appear well positioned to be deployed to regulate CSC function in the therapy of both hematologic malignancies and solid tumours." (PMID 41253780, 2025).